ATRX (ATRX chromatin remodeler)
Diseases named in the same sentence as ATRX in open-access papers (continued):
Sharing a sentence is not in itself a finding about the gene and the disease.
mental retardation (49 papers, 2006 to 2026). "ATR-X syndrome, caused by mutations in the ATRX gene, leads to intellectual disability and neurodevelopmental deficits, with previous mouse models implicating forebrain ATRX loss in cognitive impairment." (PMID 42048321, 2026). "Mutations in the ATRX gene are a primary cause of alpha-thalassemia intellectual disability X-linked (ATRX) syndrome, which is characterized by intellectual disability, autism, and a range of brain structural abnormalities, including microcephaly." (PMID 41724591, 2026). "In family 1, two affected individuals were found to have a nonsense mutation (c.109C > T; p.Arg37*) in ATRX, which is associated with intellectual disability- In hypotonic facies syndrome (OMIM 309580)." (PMID 39281811, 2024). "Alpha-thallasemia/mental retardation, X-linked chromatin remodeler, or ATRX, is an integral epigenetic regulator of cellular gene expression through the maintenance of silenced heterochromatin." (PMID 39374265, 2024). "The ATRX gene is a protein coding gene associated with alpha-thalassemia myelodysplasia syndrome and intellectual disability-hypotonic facies syndrome, X-linked." (PMID 36385957, 2022). "ATRX (on the X-chromosome, responsible for alpha-thalassaemia and mental retardation) is believed to play a role in testicular development, since the majority of mutations in ATRX result in genital abnormalities." (PMID 33568072, 2021). "His X-linked intellectual disability panel was notable for four potential disease-causing variants (in each of ATRX, FANCB, ZNF81, and ARX), but all were of undetermined significance." (PMID 34575122, 2021). "Mutations in TCF4, MEF2C, UBE3A, ZEB2 or ATRX cause phenotypically overlapping, syndromic forms of NDDs with severe intellectual disability, epilepsy and microcephaly." (PMID 31988313, 2020). "These cases expand the clinical spectrum of ATR-X syndrome and open new opportunities for the molecular diagnosis of ATRX mutations in male patients with severe global developmental delay and intellectual disabilities." (PMID 31781420, 2019). "ATR-X patients with an Arg37Stop (R37X) mutation in exon 2 exhibit mild intellectual disability, which is accompanied by reduced expression of ATRX protein in lymphoblastic cells." (PMID 30231518, 2018). "A key example is ATRX, an X-linked gene commonly mutated in individuals with syndromic and nonsyndromic intellectual disability." (PMID 28093507, 2017). "Mutations of the ATRX gene are associated with X-linked alpha thalassemia and mental retardation and encode a subunit of the chromatin-remodeling complex involved in H3.3 incorporation into heterochromatin at centromeric and telomeric regions." (PMID 25161957, 2014). "Among the differentially expressed genes in the P2 dataset, only ATRX was associated with intellectual disability according to the Online Mendelian Inheritance in Man (OMIM) database." (PMID 23227143, 2012). "Mutations in this gene lead to mental retardation which may be explained by the finding that ATRX is involved in neuronal cell survival." (PMID 19422694, 2009). "Our findings demonstrate that ATRX-related intellectual disability requires disruption of broader hippocampal or forebrain circuits to elicit cognitive impairments in learning and memory." (PMID 42048321, 2026). "Mutations in ATRX cause ATR-X syndrome, implicated in abnormal brain development and associated with severe intellectual disability." (PMID 36232428, 2022). "Molecular multigenic analysis for intellectual disability identified a previously unreported variant, p.Ile1765Met (c.5295C>G) in the SNF domain of the ATRX protein (in exon 24)." (PMID 33173999, 2020).
mental retardation (continued). "Mutations in the ATRX gene are associated with an intellectual disability syndrome referred to as ATR-Xsyndrome, characterized by autistic-like behaviours in addition to cognitive deficits, intellectual disabilities, and developmental delays." (PMID 32580781, 2020). "After consolidating intellectual disability gene lists from two databases and one recent review article, we identified eight LRRK2 interacting proteins that have previously been linked to intellectual disability: ACTB, ACTG1, ATRX, DYNC1H1, HERC2, PPP2R1A, TUBA1A, and YWHAE." (PMID 31963867, 2020).
osteosarcoma (42 papers, 2017 to 2025). A usually aggressive malignant bone-forming mesenchymal neoplasm, predominantly affecting adolescents and young adults. "Abnormal expression of ATRX or DAXX tended to be more prevalent in the osteosarcoma cell lines and was associated with significantly higher C-circle and APB scores." (PMID 41436729, 2025). "We found that SOD1 silencing was an effective method for inducing cell death in ATRX-deficient osteosarcoma cell lines; further, this approach was more effective in ATRX-null HeLa-LT than ATRX-wildtype cells." (PMID 40748226, 2025). "Presenting the data in another way, it can be seen that 67% of osteosarcoma cell lines (2/3) and 82% of fibroblast cell lines (14/17) were ATRX deficient, whereas a lung cancer cell line (SKLU-1) and a mesothelial cell line (MeT-4A) were both ATRX proficient." (PMID 40725011, 2025). "This is consistent with studies in osteosarcoma, which indicate possible mechanisms through which loss of ATRX leads to more aggressive phenotypes." (PMID 38741704, 2024). "In osteosarcoma, mutations in ATRX lead to upregulation of NF-κB, extracellular matrix remodeling, increased B3 integrin expression, and more aggressive tumor cell phenotypes, including increased growth, migration, invasion, and metastasis." (PMID 38741704, 2024). "Osteosarcoma cells utilize an alternative mechanism of telomere elongation to overcome replicative senescence, a process commonly associated with ATRX loss." (PMID 39568569, 2024). "The association between ATRX and a more aggressive sarcoma phenotype in both osteosarcoma and STS prompted our investigation of the prognostic relevance of an immunohistochemical assay to detect ATRX expression in STS." (PMID 38741704, 2024). "In exome sequencing studies involving 1,244 osteosarcoma patients, ATRX was identified as a susceptibility gene, and patients with ATRX syndrome exhibited more aggressive forms of osteosarcoma." (PMID 39479502, 2024). "The specific impact of ATRX mutation on osteosarcoma remains unstudied, but understanding this effect and the factors influencing ALT formation will be crucial for diagnosing and treating osteosarcoma." (PMID 39479502, 2024). "While ALT correlates strongly with ATRX mutations in osteosarcoma, DAXX mutations are frequently observed in pancreatic neuroendocrine tumors (PanNETs) and correlate with poorer prognosis." (PMID 37107548, 2023). "ATRX was one of the most frequently mutated genes among the 288 osteosarcoma patients examined by the American Association for Cancer Research Genomics Project, second only to TP53110-112." (PMID 36860927, 2023). "In the fourth osteosarcoma patient (M691AAA), we detected an ATRX fusion which has been suggested previously as a potential driver mutation for osteosarcoma." (PMID 37400763, 2023). "In the osteosarcoma case, the ATRX gene was identified as carrying a frameshift mutation (c.1283_1284insT) affecting exon 9 on chr23:77683973." (PMID 36673024, 2023). "The osteosarcoma sample presented mutations involving ATRX, ERCC5, and COL1A1, while the leiomyosarcoma case showed EXT2, DNM2, and PSIP1 alterations." (PMID 36673024, 2023). "Although ALT is the TMM commonly utilized by osteosarcomas, many of these tumors have wt ATRX, a gene which is frequently mutated in ALT‐positive cancers." (PMID 35920001, 2022). "One of the main discoveries of our study is that TOP3A amplification and ATRX mutation are mutually exclusive genomic events in ALT‐positive high‐grade osteosarcoma." (PMID 35920001, 2022). "Although recurrent ATRX mutations are found in osteosarcoma tumors, alterations in DAXX have only recently been reported." (PMID 30872698, 2019). "Here we characterize an osteosarcoma cell line, G292, with wild-type ATRX but a unique chromosome translocation resulting in loss of DAXX function." (PMID 30872698, 2019). "This seems to contradict the hypothesis that in osteosarcoma, either ATRX mutations or TOP3A overexpression are needed for ALT." (PMID 40725011, 2025).
osteosarcoma (continued). "We show here that another mutational event is characteristic of ATRX‐wt osteosarcomas." (PMID 35920001, 2022). "ATRX mutations were also observed in 8 osteosarcomas, with similar associations to telomere length." (PMID 35585047, 2022). "Around 29% of osteosarcomas harbour somatic mutations in ATRX." (PMID 31741049, 2020). "ATRX plays an important tumor-suppressor role in OS, and deletion of this gene leads to tumor cell growth, migration, and invasion, and was one of the most commonly mutated genes in 288 osteosarcoma patients surveyed by the Genomics Evidence Neoplasia Information Exchange consortium in the USA." (PMID 39654890, 2024). "However, it is unclear whether there is an association between osteosarcoma and germline ATRX mutations." (PMID 35444965, 2022). "The role of ATRX mutations in osteosarcoma genesis is largely unknown." (PMID 31741049, 2020). "Further, ATRX loss was significantly associated with DRG2 downregulation in several other tumour types which are frequently ALT-positive, such as HGG, osteosarcoma, paraganglioma, and phaeochromocytoma." (PMID 39921567, 2025). "Therapeutic manipulation of ROS levels to outside of the optimal level provides a novel approach to treatment for ATRX-deficient ALT cancers, including osteosarcoma, LGG and other ALT-positive tumours." (PMID 39921567, 2025). "In osteosarcoma, the ALT-positive phenotype, which is typically associated with ATRX mutation or loss of expression, is also observed in high-grade pediatric osteosarcoma, where telomere maintenance occurs despite wild-type ATRX expression." (PMID 39479502, 2024). "In other work, wild-type DAXX was restored to the ALT + G292 osteosarcoma cell line, in which ATRX is wild type but DAXX has undergone a fusion event with the non-canonical kinesin KIFC3." (PMID 37107548, 2023). "Our results reveal that a majority of pediatric osteosarcomas were able to maintain their telomeres by ALT while expressing wt ATRX." (PMID 35920001, 2022). "The results emphasize the potential interest in developing TOP3A inhibitors for treatment of ALT‐positive ATRX‐wt osteosarcomas." (PMID 35920001, 2022). "Strikingly, previous reports showed that ATRX mutation and/or loss of protein expression is detectable in only 30% of ALT‐positive osteosarcomas." (PMID 35920001, 2022). "To confirm this result, we analyzed the seven osteosarcoma tumor samples for ATRX, DAXX, SMARCAL1, H3.3, and SLX4IP protein expression by immunoblotting." (PMID 31447390, 2019). "Strikingly, when ectopic ATRX is expressed in ATRX-null human osteosarcoma U2OS cells, the ALT pathway is reduced." (PMID 29250704, 2018). "However, NGS revealed a complex genome lacking the characteristic EWSR1-associated rearrangements and instead identified deletions in RB1, PTCH1, and ATRX, confirming the diagnosis of osteosarcoma." (PMID 40115314, 2025). "A study reports that ATRX expressed significantly higher in osteosarcoma compared with normal." (PMID 36245994, 2022). "The datasets and computer code produced in this study are available at the ArrayExpress database with the following accession number: RNA Affymetrix GeneChip: E‐MTAB‐11743 (Title: Alternative Lengthening of Telomeres (ALT) and ATRX inactivation in high‐grade pediatric osteosarcomas." (PMID 35920001, 2022).
osteosarcoma (continued). "When the loss of ATRX and DAXX is detected, the chance of the tumor being ALT positive varies from 83% in leiomyosarcoma to 100% in osteosarcoma and liposarcoma, suggesting that mutation analysis of the ATRX and DAXX gene is a reliable predictor of the ALT positivity in certain cancers." (PMID 34069193, 2021). "Another study found that ectopic ATRX expression within telomerase-deficient, ALT-positive osteosarcoma epithelial (U-2 OS) cells led to DAXX-dependent reduction of several features of the ALT phenotype, signifying that ATRX loss is imperative for the maintenance of the ALT phenotype." (PMID 29034211, 2017). "Therefore, we asked whether we could identify defects in ATRX/DAXX/H3.3 using RNA sequencing on a panel of 13 osteosarcoma cell lines." (PMID 30214690, 2018). "Surprisingly, the SV40 LT-transformed ATRX−/− fibroblast clones and the bulk culture showed all key features of ALT cells at or exceeding the level of the established ALT osteosarcoma line U2OS." (PMID 36805596, 2023). "Here, we have shown that TOP3A amplification and overexpression is an alternative to ATRX inactivation, and the most frequent genetic event identified in ALT‐positive high‐grade pediatric osteosarcoma." (PMID 35920001, 2022). "Here, we report that most high‐grade pediatric osteosarcomas maintain their telomeres by ALT, and that the majority of these ALT tumors are ATRX wild‐type (wt) and instead carry an amplified 17p11.2 chromosomal region containing TOP3A." (PMID 35920001, 2022). "In osteosarcoma cells, RHPS4 effectiveness seems to be unlinked from both the genetic status of ATRX and the active TMM, as demonstrated by the very similar sensitivity of HOS telomerase-positive cells to the compound (IC50 value: 1.2 μM)." (PMID 32183119, 2020). "Using immunofluorescence imaging, we assayed the localization of ATRX and DAXX in G292 and the TERT + osteosarcoma line SJSA1." (PMID 30872698, 2019). "We confirmed protein expression of ATRX and DAXX in G292 by western blot, revealing normal ATRX protein expression but aberrant size of DAXX protein in comparison with other osteosarcoma cell lines." (PMID 30872698, 2019). "Therefore, we went on to test co-treatment with CPT and shSOD1 in a natural ALT-positive, ATRX-negative osteosarcoma cell line, U2OS." (PMID 40748226, 2025). "The same effect was not, however, observed in osteosarcoma or HGG, indicating that hypoxia might not be a root cause of elevated ROS in these lines, or that hypoxia plays a role in both ATRX-wildtype and ATRX-null tumours of this type." (PMID 39921567, 2025). "This discrepancy between a high level of ALT and a low proportion of ATRX inactivation led us to hypothesize that ATRX alteration may not be the only alteration responsible for the ALT mechanism in osteosarcoma." (PMID 35920001, 2022). "Among the 10 ALT osteosarcoma cell lines, 5 harbored ATRX alterations and no TOP3A amplification, 2 harbored no ATRX alteration and TOP3A amplification, and 3 neither of the 2; statistical analysis, however, gave a non-significant result (p = 0.44)." (PMID 40725011, 2025).
sarcoma (41 papers, 2013 to 2025). A usually aggressive malignant neoplasm of the soft tissue or bone. "A genetic analysis of a large cohort of 2138 sarcomas spanning over 45 sarcoma subtypes identified >10% loss of ATRX expression across various soft tissue sarcoma subtypes, with uLMS having the highest mutation rate of up to one in three cases." (PMID 41228336, 2025). "Our study reinforces ATRX mutations as a marker of poor prognosis in leiomyosarcoma, aligning with prior observations in other sarcoma subtypes and extending this association to both uterine and non-uterine disease in a leiomyosarcoma-specific cohort." (PMID 41228336, 2025). "As recently noted in the literature, ATRX mutation was associated with a more aggressive sarcoma and worse overall survival compared to ATRX-wt." (PMID 40563612, 2025). "Loss of function genetic alterations in ATRX are highly recurrent in several cancers including gliomas, pancreatic neuroendocrine tumors, and multiple sarcoma subtypes." (PMID 38477352, 2024). "ATRX mutation is also associated with reduced mast cell infiltration in a xenograft model of sarcoma." (PMID 38473300, 2024). "Similar epigenetic effects were observed in an ATRX deficiency patient-derived sarcoma cell compared to a wildtype isogenic control." (PMID 38477352, 2024). "Sarcomas, which are cancers of connective tissues, have recurrent loss of ATRX in up to 30% of specific subtypes, suggesting the potential importance of ATRX deficiency in sarcoma biology and possibilities for precision medicine approaches to treatment." (PMID 38477352, 2024). "As our understanding of how ATRX influences aggressivity in sarcoma continues to be developed, an important aspect of this will be to explore therapeutic vulnerabilities in patients with ATRX mutation or loss." (PMID 38741704, 2024). "In their diverse sarcoma panel, Koelsche and colleagues found that the prevalence of complete nuclear ATRX loss in UPS is higher than that of all other sarcomas (38%; 20/52)." (PMID 34069193, 2021). "Loss of ATRX is highly associated with alternative lengthening of telomeres, and it is frequently found in complex sarcomas." (PMID 34659131, 2021). "These two findings show that ATRX loss can influence the regulation of immune response in sarcomas, probably by limiting mast cell recruitment, as evidenced by the lower proportion of tumor-infiltrating mast cells upon ATRX down-expression." (PMID 33946962, 2021). "The precise mechanism involved in ATRX loss that changes the immune microenvironment of sarcomas needs to be deciphered." (PMID 33946962, 2021). "This is in stark contrast to two previously published studies of ATRX loss in a variety of sarcoma subtypes, which demonstrated loss of ATRX in 1/17 (6%) and 2/47 (4%) of MPNST samples, respectively." (PMID 29796169, 2018). "While the role of ATRX deficiency in the alternative lengthening of telomeres pathway is well described in sarcomas and other ATRX deficient cancers, the chromatin-specific consequences of ATRX loss are not fully understood in the context of disease mechanisms." (PMID 38477352, 2024). "Recently, the association between ATRX and a more aggressive sarcoma phenotype has been shown." (PMID 38741704, 2024). "ATRX pathogenic variant is one of the most common genomic alterations in sarcoma." (PMID 39696530, 2024). "Because deletion of Atrx sensitizes sarcoma cells to oncolytic herpes virus and radiation therapy, tumors with loss-of-function mutations in ATRX may be particularly sensitive to the combination of oncolytic herpesvirus with radiation therapy." (PMID 37200088, 2023). "In vivo experimentation revealed a new role of ATRX, as its alteration was associated with a poorer outcome exclusively in an immunocompetent murine host, and with down-expression of immune-related genes in poorly differentiated pleomorphic human sarcomas." (PMID 33946962, 2021).